RHO (rhodopsin)
Diseases named in the same sentence as RHO in open-access papers (continued):
Sharing a sentence is not in itself a finding about the gene and the disease.
retinitis pigmentosa (continued). "The mutation S343N in a rhodopsin phosphorylation site in the C-terminus is likely pathogenic for retinitis pigmentosa, which induces progressive loss of vision over time." (PMID 36830724, 2023). "Over 100 mutations in the rhodopsin gene have been linked to a spectrum of retinopathies that include retinitis pigmentosa and congenital stationary night blindness." (PMID 35850308, 2022). "Retinitis pigmentosa is largely due to missense mutations in RHO (rhodopsin), a GPCR, that cause its misfolding, retention in the ER, and premature degradation." (PMID 36743458, 2022). "Rhodopsin (RHO) mutations are responsible for 25–40% of the dominant cases of retinitis pigmentosa (RP) with different severity and progression rates." (PMID 35516813, 2022). "RHO mutants that cause retinitis pigmentosa, such as RHOP23H, misfold with degradation intermediates stabilized via a disulfide." (PMID 36743458, 2022). "In total, 30–40% of cases of retinitis pigmentosa (RP) have an autosomal dominant pattern of inheritance with Rhodopsin (RHO) being the most commonly mutated gene (RP4, OMIM 613731)." (PMID 35414130, 2022). "Highly efficient gene disruption through CRISPR/Cas9 makes it a promising technique to treat the dominant mutations in rhodopsin and retinitis pigmentosa." (PMID 36232782, 2022). "Uncharacteristically fast rod recovery kinetics are facets of both human patients and transgenic animal models with a P23H rhodopsin mutation, a prevalent cause of retinitis pigmentosa (RP)." (PMID 33509952, 2021). "In the retina, HSP90 is induced in retinitis pigmentosa (RP), the most common form of inherited photoreceptor degeneration caused by a mutation in the rhodopsin gene." (PMID 34495872, 2021). "In humans, mutations in the RHO gene are associated to the onset of retinitis pigmentosa and to such other autosomal dominant genetic diseases as congenital stationary night blindness." (PMID 33920623, 2021). "Chronic endoplasmic reticulum stress resulting from misfolding of the visual pigment rhodopsin (RHO) can lead to loss of rod photoreceptors, which initiates retinitis pigmentosa, characterized initially by diminished nighttime and peripheral vision." (PMID 33214223, 2021). "Four families (families 14, 15, 48 and 54) developed retinitis pigmentosa caused by RHO mutations, and the patients in these families manifested night blindness in childhood, visual field defects or tubular visual fields and retinitis pigmentosa." (PMID 33781268, 2021). "Mutations in rhodopsin gene (RHO) are a frequent cause of retinitis pigmentosa (RP) and less often, congenital stationary night blindness (CSNB)." (PMID 33669941, 2021). "There are many examples of temperature-sensitive rhodopsin variants, the misfolding of which is associated with the molecular basis of retinitis pigmentosa." (PMID 34756884, 2021). "We identified a novel heterozygous nonsense mutation of RHO gene in a Chinese family with retinitis pigmentosa by target region sequencing and our bioinformatics analysis indicated that the mutation is pathogenic." (PMID 34635090, 2021). "To gain insights into the basis of these variations, we recently surveyed mutagenic trends in the class A G-protein-coupled receptor rhodopsin, the misfolding of which causes retinitis pigmentosa (RP)." (PMID 34756884, 2021). "A novel heterozygous nonsense mutation (c.1015 A > T, p.Lys339Ter, p.K339X) within RHO, which cosegregated with retinitis pigmentosa phenotype was detected in this family." (PMID 34635090, 2021). "Our results can broaden the spectrum of RHO gene mutation and enrich the phenotype-genotype correlation of retinitis pigmentosa." (PMID 34635090, 2021). "Rod photoreceptors show abnormal neurite sprouting in humans with retinitis pigmentosa, cats with rod/cone dysplasia, and pigs carrying a mutation in the rhodopsin gene." (PMID 34122012, 2021).
retinitis pigmentosa (continued). "While many rhodopsin mutations have well-understood consequences that lead to cell death, the disease association of several rhodopsin mutations identified in retinitis pigmentosa patients, including F220C and F45L, has been disputed." (PMID 32371886, 2020). "The aggregation of P23H, a mutated rhodopsin found in retinal cells and seen in retinitis pigmentosa, leads to the impairment of the ubiquitin proteasome system, an important protein degradation system." (PMID 32351353, 2020). "Retinitis pigmentosa (RP) is a group of blinding disorders caused by diverse mutations, including in rhodopsin (RHO)." (PMID 33046772, 2020). "For example, many genes with causative mutations leading to Retinitis Pigmentosa, including RHO, NRL, and NR2E3 demonstrated foveal rod enrichment." (PMID 32555229, 2020). "We addressed this issue in an established mouse model of Retinitis Pigmentosa caused by the P23H mutation in rhodopsin." (PMID 32960171, 2020). "Pro23His (P23H) transgenic albino rat strains are widely used models for the most common rhodopsin gene mutation associated with the autosomal dominant form of retinitis pigmentosa." (PMID 33224023, 2020). "It was recently demonstrated that three enigmatic mutants of rhodopsin, known to cause the blinding disease retinitis pigmentosa, inhibit rhodopsin dimerization." (PMID 31240247, 2019). "Rhodopsin, the visual pigment of the rod photoreceptors, was the first identified genetic cause of retinitis pigmentosa (RP) disease and mutations in the rhodopsin gene (RHO) are the most common." (PMID 31100078, 2019). "Mutations in rhodopsin are the most prevalent cause of blinding diseases such as retinitis pigmentosa (RP), due to initial rod photoreceptor degeneration followed by the decline of cone photoreceptors." (PMID 31835521, 2019). "For example, the most frequent mutation found in human RHO that causes retinitis pigmentosa is a missense variant (p.P23H) that is inherited in an autosomal dominant fashion." (PMID 30693015, 2018). "In humans, there are more than 100 different mutations in Rh (human gene symbol: RHO) that cause progressive eye diseases known as retinitis pigmentosa (OMIM #268000)." (PMID 30693015, 2018). "Pathogenic mutations in genes that regulate RHO trafficking such as CRB1 (Crumbs in fly) also cause retinitis pigmentosa in humans and have also been shown to mediate retinal degeneration in Drosophila." (PMID 30693015, 2018). "Some 40% of Retinitis Pigmentosa cases display autosomal dominant inheritance, and 25–30% of these are attributable to mutations in RHO, the gene coding for rhodopsin, the light sensitive protein of rod photoreceptors." (PMID 28720880, 2017). "Protein misfolding caused by inherited mutations leads to loss of protein function and potentially toxic ‘gain of function’, such as the dominant P23H rhodopsin mutation that causes retinitis pigmentosa (RP)." (PMID 28065882, 2017). "By using this technology to create genomic DNA breakpoints and indel mutations, we were able to generate rhodopsin knockout and gain of function phenotypes in X. laevis tadpoles that model the human conditions of recessive and dominant retinitis pigmentosa." (PMID 28761125, 2017). "We have analyzed the effect of the flavonoid quercetin on the conformation, stability and function of the G protein-coupled receptor rhodopsin, and the G90V mutant associated with the retinal degenerative disease retinitis pigmentosa." (PMID 28894166, 2017). "In a mutant Rhodopsin mouse model of retinitis pigmentosa (RP) causing progressive photoreceptor death—but sparing retinal ganglion cells—TrkC.T1 and NT-3 ligand are upregulated in Müller glia." (PMID 29242588, 2017). "Retinitis pigmentosa is often caused by mutations that affect the activity or transport of rhodopsin, but some mutations cause disease even though an apparently functional protein is produced." (PMID 27694816, 2016).
retinitis pigmentosa (continued). "Retinitis pigmentosa (RP) is a blinding disease often associated with mutations in rhodopsin, a light-sensing G protein-coupled receptor and phospholipid scramblase." (PMID 27694816, 2016). "Later evidence in human patients showed that mutations in rhodopsin and related genes are major causes of retinitis pigmentosa, the most common form of retinal degeneration disease." (PMID 26659849, 2015). "In this context, γ-synuclein has shown some neuroprotective effects on a photoreceptor cell line expressing a retinitis pigmentosa-causative dominant allele of the rhodopsin gene, P23H, encoding a misfolded, cytotoxic variant of this protein." (PMID 24040246, 2013). "Recently, a transgenic rabbit with rhodopsin Pro 347 Leu mutation was generated as a model of retinitis pigmentosa (RP), which is characterized by a gradual loss of vision due to photoreceptor degeneration." (PMID 22558356, 2012). "This trend is also observed in animal models; for example in VPP mice carrying rhodopsin mutations and exhibiting a retinitis pigmentosa phenotype, rapid loss of rod cells is followed by a slow degeneration of cone photoreceptor cells." (PMID 22427845, 2012). "Retinitis pigmentosa is a common form of inherited neurodegeneration often caused by mutations in the photosensitive pigment rhodopsin." (PMID 20927324, 2010). "The best characterized of theseare mutations in the molecular light sensor, rhodopsin, which cause autosomaldominant retinitis pigmentosa." (PMID 18490186, 2008). "Despite these hypotheses, it is currently unclear whether mutations in the rhodopsin gene or other retinitis pigmentosa-associated genes may affect embryonic cell fate determination." (PMID 41562848, 2026). "Dominant mutations in RHO lead to improper folding of this protein, which, in turn, causes endoplasmic reticulum stress, impaired transport, retinal inflammation, and photoreceptor death; retinitis pigmentosa can also be caused by RHO deficiency or mutations in other genes." (PMID 40650152, 2025). "Abnormal levels of misfolded protein aggregations are seen in mouse models of retinitis pigmentosa carrying MS variants of rhodopsin, identified by positive staining with the PROTEOSTAT protein aggregation dye, which fluoresces when trapped in aggregated protein formations." (PMID 41270749, 2025). "Zinc is indispensable for many essential physiological processes of the retina, including regulating rhodopsin stabilization and retinol metabolism, while its systemic deficiency may lead to retinitis pigmentosa as well as abnormal visual dark adaptation." (PMID 37817192, 2023). "Additionally, WDR17 was found among genes correlating with rhodopsin expression and mapped to human loci associated with retinitis pigmentosa." (PMID 37172722, 2023). "Although RP is a genetically heterogeneous disease, most cases of RP are monogenic, and mutations in the rhodopsin gene (rho), Usher syndrome 2A gene (ush2a), and retinitis pigmentosa GTPase regulator gene (rpgr) engage in about 30% of all cases of retinitis pigmentosa." (PMID 37685886, 2023). "Retinitis pigmentosa (RP) encompasses several clinical conditions caused by a large number of genetic alterations that, alone or in combination, cause damage to the molecular processes necessary for the creation, storage, utilization or recovery of rhodopsin." (PMID 37762059, 2023). "Those cell lines were a Wild-Type iPSC line from a patient without any ophthalmologic disease and no genetic variants related to retinal dystrophies (C1) and an iPS cell line derived from a patient with Retinitis Pigmentosa carrying an autosomal dominant RHO mutation." (PMID 35806438, 2022). "Some characteristic mutations present in rhodopsin gene may be involved in retinitis pigmentosa, a group of diseases characterized by photoreceptor cell death in the retina and subsequent vision loss." (PMID 35627905, 2022).
retinitis pigmentosa (continued). "These P23H and wild-type rhodopsin proteomic datasets from native retinas provide a resource for additional studies about rhodopsin protein quality control, rod cell biology, and pathomechanisms underlying retinitis pigmentosa." (PMID 36258031, 2022). "Mutations in rhodopsin cause inherited retinal degenerative diseases such as retinitis pigmentosa." (PMID 34069614, 2021). "Around 200 mutations in the rhodopsin gene (RHO) cause retinal diseases, in most patients in the form of retinitis pigmentosa (RP), although other phenotypes have also been described, including sector RP, pericentral RP, congenital stationary night blindness (CSNB), and retinitis punctata albescens." (PMID 33669941, 2021). "For example, RHO variants may cause stationary (congenital stationary night blindness) or progressive disease (retinitis pigmentosa) even within the same family." (PMID 34449556, 2021). "Recent evidence suggests that certain flavonoids could help stabilize the correctly folded conformation of the visual photoreceptor protein rhodopsin and offset the deleterious effect of retinitis pigmentosa mutations." (PMID 34199888, 2021). "We tested this hypothesis using an established mouse model of the most common form of Retinitis Pigmentosa (RP) caused by a dominant P23H mutation in the rod visual pigment, rhodopsin." (PMID 32960171, 2020). "The accumulation of misfolded rhodopsin within the ER is a prominent cause of retinitis pigmentosa." (PMID 30096827, 2018). "Mutations affecting the N-glycosylation status of rhodopsin result in retinitis pigmentosa (RP)." (PMID 24569140, 2014). "Rhodopsin mutations are associated with the autosomal dominant form of retinitis pigmentosa." (PMID 25530840, 2014). "For sensitive detection of rare gene repair events in terminally differentiated photoreceptors, we generated a knockin mouse model by replacing one mouse rhodopsin allele with a form of the human rhodopsin gene that causes a severe, early-onset form of retinitis pigmentosa." (PMID 25264759, 2014). "On the other hand, ER stress and UPR signaling are known to be related to the onset or progression of many ocular diseases, such as retinitis pigmentosa caused by mutated rhodopsin, primary open angle glaucoma, diabetic retinopathy, and age-related macular degeneration." (PMID 23383089, 2013). "MicroRNA expression profiling showed that the retina of mice carrying a rhodopsin mutation that leads to retinitis pigmentosa have notably different microRNA profiles from wildtype mice; further in silico analyses identified potential retinal targets for differentially regulated microRNAs." (PMID 18034880, 2007). "The development of small molecules chemical chaperones for rhodopsin provides an attractive approach to promote its proper folding and trafficking, which would allow to slow down photoreceptor cell death and vision loss in patients affected by retinitis pigmentosa and Leber congenital amaurosis." (PMID 33114011, 2020). "Mutations in the gene encoding rhodopsin (RHO) can cause opsin misfolding or reduce its stability, resulting in retinal degenerative disorders such as retinitis pigmentosa (RP)." (PMID 40509215, 2025). "This study underscores the protective effect of non-invasive ES in rhodopsin knockout-induced retinal degenerative disorders, providing a foundation for developing targeted therapeutic interventions for retinitis pigmentosa." (PMID 39206091, 2024). "Suppression of mutant rhodopsin gene (RHO) in Retinitis Pigmentosa to prevent degeneration of photoreceptors." (PMID 39439625, 2024). "A heterozygote RhoP23H/WT knock-in mouse is an established model of human blindness called retinitis pigmentosa, expressing both mutant and WT rhodopsin in rod photoreceptors." (PMID 37450596, 2023).
retinitis pigmentosa (continued). "Antisense oligonucleotides (ASOs) were used for allele-specific targeting of the Huntingtin gene, and rhodopsin P23H gene in retinitis pigmentosa, where ASO-mediated silencing led to long-term effects in rodent models." (PMID 37864244, 2023). "In a rhodopsin P23H heterozygous mouse model of retinitis pigmentosa, this strategy quadrupled the number of surviving photoreceptors in the inferior retina of 6 month-old mice." (PMID 37123404, 2023). "Mutations in the rhodopsin gene that lead to the development of autosomal dominant forms of retinitis pigmentosa are divided into three different classes, distinguished by the dysfunction of rhodopsin and the nature of its accumulation in cell culture." (PMID 37893030, 2023). "Here, we used CRISPR-Cas9-mediated rhodopsin (rho) gene editing to generate models of retinitis pigmentosa in both X. laevis and X. tropicalis." (PMID 35269429, 2022). "Our mouse model of retinitis pigmentosa is unique in that it introduces a bright fluorescent Tag-RFP-T protein tag onto the mutant P23H form of rhodopsin." (PMID 35587875, 2022). "Efficient CRISPR/Cas9-mediated editing of the rhodopsin (rho) gene was previously reported in both Xenopus laevis and zebrafish and was shown to generate features of retinitis pigmentosa." (PMID 35269429, 2022). "Michael Robichaux is first author on ‘Subcellular localization of mutant P23H rhodopsin in an RFP fusion knock-in mouse model of retinitis pigmentosa’, published in DMM." (PMID 35587875, 2022). "We here developed rhodopsin gene editing-based models of retinitis pigmentosa in two Xenopus species, Xenopus laevis and Xenopus tropicalis, by using CRISPR/Cas9 technology." (PMID 35269429, 2022). "We modeled retinitis pigmentosa by expressing mutant rhodopsin (Rh1G69D) and tauopathy by expressing TauV337M." (PMID 33983927, 2021). "The transplantation of bone marrow-derived MSCs was shown to rescue photoreceptor cells in dystrophic retina of rhodopsin knockout mice, suggesting a therapeutic benefit in retinitis pigmentosa." (PMID 33467640, 2021). "Accumulation of misfolded and mistrafficked rhodopsin on the endoplasmic reticulum of photoreceptor cells has a pivotal role in the pathogenesis of retinitis pigmentosa and a subset of Leber’s congenital amaurosis." (PMID 33114011, 2020). "It rescues glucocerebrosidase in fibroblasts of Gaucher patients both in terms of quantity and in terms of maturation and prevents aggregation of a missense mutant of rhodopsin, P23H, which is frequently encountered in retinitis pigmentosa." (PMID 31940970, 2020). "In our study, the JNK1–c-Jun–Notch1 axis influenced some transcriptional factors and three opsins, such as Crx and Rhodopsin, which are drug targets of retinitis pigmentosa." (PMID 31450635, 2019). "Rhodopsin mislocalization, which is characteristic of many forms of retinitis pigmentosa, is thought to be a major contributing factor in photoreceptor cell death." (PMID 30228302, 2018). "In rhodopsin, the G114V3.29 and Q184P4.73 (Ballesteros and Weinstein numbering used) variants have been shown to cause protein misfolding resulting in retinitis pigmentosa in patients." (PMID 24465800, 2014). "Mutations in both of these proteins are associated with a variety of blinding retinal diseases including retinitis pigmentosa (RP-rhodopsin and RDS), congenital stationary night blindness (CSNB-rhodopsin), and various forms of macular dystrophy (MD-RDS)." (PMID 24897172, 2014). "This is in contrast to rhodopsin, where the nsSNP A164V destabilizes helix packing resulting in protein misfolding and retinitis pigmentosa." (PMID 22272267, 2012). "Similar to the decreased thermal stability and constitutive activity observed for the nsSNP A160T, a recent study on the rhodopsin retinitis pigmentosa mutant, G90V, shows that it has low thermal stability in the dark state and is constitutively active." (PMID 22272267, 2012).